TNFSF15 (TNF superfamily member 15)
Description:
Cytokine that signals through TNFRSF25 receptor. Functions as a T-cell costimulator, that increases IL-2 responsiveness and secretion of proinflammatory cytokines which enhances T-cell activation, proliferation and the survival of activated T-cells. Inhibits vascular endothelial growth and angiogenesis (in vitro). Binds to the decoy receptor TNFRSF6B, blocking the activation normally triggered by TNFSF15 and leading to decreased T-cell activation and reduced inflammation.
Synonyms: TL1; TL1A; VEGI; VEGI192A; MGC129934; MGC129935; TNLG1B
Tractability: Small molecule: it has a binding pocket of medium quality. Antibody: its Gene Ontology location is reachable by antibodies, with high confidence; UniProt places it where antibodies can reach, with medium confidence; UniProt predicts a signal peptide or a membrane-spanning region.
Gene: Protein-coding gene on chromosome 9 (114,784,652 to 114,806,039, reverse strand). Ensembl gene ENSG00000181634.
Subcellular location: Membrane; Secreted (Tumor necrosis factor ligand superfamily member 15, secreted form)
Subcellular location (Human Protein Atlas): Nuclear membrane; Cytosol; Nucleoplasm; Predicted to be secreted
Pathways (Reactome):
Immune System: TNFs bind their physiological receptors
Gene Ontology:
Molecular function: protein binding; cytokine activity; signaling receptor binding; tumor necrosis factor receptor binding
Biological process: activation of NF-kappaB-inducing kinase activity; cell surface receptor signaling pathway; positive regulation of canonical NF-kappaB signal transduction; positive regulation of extrinsic apoptotic signaling pathway; signal transduction; cell communication; immune response; signaling
Cellular component: plasma membrane; membrane; extracellular region
Genetic constraint (gnomAD): Loss-of-function variants: 15 observed, 23.45 expected, observed/expected ratio (o/e) 0.64, 90% interval 0.43 to 0.99. The upper end of that interval is the gene's LOEUF score, 0.99, which puts it in group 4 of 6, group 1 being the genes least tolerant of losing a copy. Missense variants: 246 observed, 259.87 expected, observed/expected ratio (o/e) 0.95, 90% interval 0.85 to 1.05. Synonymous variants: 100 observed, 97.67 expected, observed/expected ratio (o/e) 1.02, 90% interval 0.87 to 1.21.
Homologues: Orthologues: chimpanzee TNFSF15 (99% identical), macaque TNFSF15 (98% identical), pig TNFSF15 (88% identical), rabbit TNFSF15 (81% identical), guinea pig TNFSF15 (78% identical), rat Tnfsf15 (70% identical), mouse Tnfsf15 (67% identical), dog TNFSF15 (65% identical), tropical clawed frog tnfsf15 (38% identical). Paralogues in human: FASLG (27% identical), TNF (24% identical), TNFSF14 (24% identical), LTA (22% identical), TNFSF10 (21% identical), CD40LG (20% identical), LTB (20% identical), TNFSF11 (17% identical).
Diseases named in the same sentence as TNFSF15 in open-access papers:
TNFSF15 is named in the same sentence as 128 diseases in open-access papers, as found by Europe PMC text mining. Sharing a sentence is not in itself a finding about the gene and the disease. The quoted sentences say what the papers report.
inflammatory bowel disease (38 papers, 2011 to 2025). A spectrum of small and large bowel inflammatory diseases of unknown etiology. "Genome-wide association studies have shown that the genetic variants of human TNFSF15 are associated with inflammatory bowel disease." (PMID 39542253, 2024). "Tumor necrosis factor-like cytokine 1A (TL1A, TNFSF15) is implicated in inflammatory bowel disease, modulating the location and severity of inflammation and fibrosis." (PMID 33097818, 2020). "Nevertheless, several studies have examined the relationship between TNFSF15 polymorphisms and susceptibility to inflammatory bowel disease and Crohn’s disease in Japanese and European populations." (PMID 25251497, 2014). "TNFSF15, also known as TL1A, is a potential vascular endothelial cell growth inhibitor, and it is related to inflammatory diseases of the gut, such as inflammatory bowel disease (IBD) and irritable bowel syndrome (IBS)." (PMID 24369539, 2013). "In addition, TNFSF15 upregulation was observed in various autoimmune diseases, such as rheumatoid arthritis and inflammatory bowel disease." (PMID 38561797, 2024). "In previous studies, it was reported that TNFSF15 took part in the development of diverse T cell-mediated autoimmune diseases, such as inflammatory bowel disease (IBD), and in experimental models such as chronic murine ileitis and autoimmune encephalomyelitis." (PMID 25330517, 2014).
Crohn disease (28 papers, 2009 to 2025). A gastrointestinal disorder characterized by chronic inflammation involving all layers of the intestinal wall, noncaseating granulomas affecting the intestinal wall and regional lymph nodes, and transmural fibrosis. "For example, a synonymous SNP in the TNFSF15 gene (i.e., rs3810936) was linked with Crohn’s disease." (PMID 36117180, 2022). "Genome-wide association studies have revealed that IL23R and five additional genes involved in Th17 differentiation (IL12B, JAK2, STAT3, CCR6 and TNFSF15) are associated with susceptibility to Crohn’s disease." (PMID 36498596, 2022). "TL1A (TNFSF15) is a major Crohn's disease (CD) susceptibility gene, especially in the East Asian population, and is also known to be associated with some clinical phenotypes, such as stricturing and penetrating behavior." (PMID 33319044, 2020). "Pertaining to IBD, genetic variants of TNFSF15 show elevated TL1A host expression, and are associated with a severe Crohn’s Disease (CD) phenotype that features intestinal fibrostenosis and need for surgery." (PMID 33097818, 2020). "Polymorphisms of Tnfsf15 (encoding TL1A) has been linked to susceptibility to Crohn’s disease (CD) by genome-wide association studies in humans." (PMID 31358760, 2019). "Of note, genes implicated in Crohn’s disease such as Cldn8 (encodes tight junction protein claudin 8) and Tnfsf15 were also downregulated in SERT KO mice." (PMID 29666456, 2018). "The TNFSF15/TNFSF8 region is a well-known locus associated with Crohn’s disease (CD) susceptibility." (PMID 28261213, 2017). "Recently, increased levels in sera and genetic polymorphisms of TNFSF15 have been observed in inflammatory diseases that are caused by altered immunological reactions such as Crohn’s disease or ulcerative colitis." (PMID 27765052, 2016). "We examined the association of seven single nucleotide polymorphisms (SNP) in the TNFSF15 gene with Crohn's disease (CD) and ulcerative colitis (UC) in the Indian population." (PMID 25501099, 2014). "For example, rs3810936, a synonymous SNP in TNFSF15 was found to be significantly associated with Crohn's disease in Japanese, Korean, and Caucasian." (PMID 21042586, 2010). "Interestingly, the well-established IBS and Crohn’s Disease susceptibility gene Tnfsf15, was differentially expressed in SERT KO30,31." (PMID 29666456, 2018). "TNFSF15, encoding a member of the tumor necrosis factor superfamily of cytokines, is primarily expressed in endothelial cells and has previously been implicated in susceptibility to Crohn’s disease." (PMID 28973304, 2017). "Additionally, TNFSF15 single nucleotide polymorphisms and haplotypes were found to be strongly correlated to Crohn’s disease in Japanese patients." (PMID 25330517, 2014). "Genetic variations in the tumor necrosis factor ligand superfamily member 15 (TNFSF15) and interleukin 23 receptor (IL23R) genes, both involved in suppressing inflammation, have been associated with an increased risk of developing Crohn’s disease." (PMID 40392591, 2025). "Tumor necrosis factor ligand superfamily member 15 (TNFSF15) and IL23R are the two genes susceptible to Crohn’s disease that regulate ILC3s and TH17 cells and that are responsible for the induction of IL-17 and IL-22 in controlling symbiotic microorganisms." (PMID 33316984, 2020). "To date, only one gene (TNFSF15) has been identified and validated as a Crohn’s disease (CD)-associated gene in non-Caucasian populations." (PMID 24945726, 2014). "Occurrence of variants in the TNFSF15 gene may influence the expression and function of TNFSF15 (TL1A) which may eventually result in disproportionate immune response in the bowel and altered cytokine production as seen in Crohn's disease." (PMID 25501099, 2014). "For main effects, JAK2, TNFSF15, ZNF365 and PTPN22 showed consistent small P‐values in the original sequencing data as well as the validation with IBD and Crohn's disease data sets." (PMID 29441677, 2018).
autoimmune disease (26 papers, 2011 to 2025). A disorder resulting from loss of function or tissue destruction of an organ or multiple organs, arising from humoral or cellular immune responses of the individual to their own tissue constituents. "For example, Asian-specific haQTLs provided novel candidate variants in gene loci associated with leprosy (SIGLEC5, TNFSF15) and autoimmune disease (CARD9, IRF5, IL27, FOS) (nd 48)." (PMID 35102304, 2022). "Polymorphisms of the TNFSF15 gene that encodes TL1A are associated with the pathogenesis of irritable bowel syndrome, leprosy, and autoimmune diseases, including IBD, AS, and primary biliary cirrhosis (PBC)." (PMID 24453414, 2013). "used allele-specific expression measurements to demonstrate that IBD-protective alleles in the chromosome 9q32 locus enhance expression of TNFSF15 (MIM: 604052), suggesting agonists of TNFSF15 as potential therapies for treating autoimmune diseases." (PMID 33798443, 2021).
rheumatoid arthritis (24 papers, 2011 to 2025). A chronic, systemic autoimmune disorder characterized by inflammation in the synovial membranes and articular surfaces. "TNFSF-15, also known as TL1A, is a well-known inflammatory mediator in rheumatoid arthritis." (PMID 39408838, 2024).
colitis (22 papers, 2009 to 2025). Inflammation of the colon. "In addition, the TNF-like ligand 1A encoded by Tnfsf15 plays an important role in mucosal healing in DSS-induced colitis." (PMID 39542253, 2024). "Thus TNFSF15 via TL1A augments Th1 responses in the intestine and TL1A overexpression in lymphoid and myeloid cells has been shown to lead to spontaneous colitis in experimental animals." (PMID 25501099, 2014).
asthma (21 papers, 2014 to 2026). "Notably, ulcerative colitis was associated with the pleiotropic TNFSF15 gene (within the asthma L-GRN), which is associated with both childhood asthma and ulcerative colitis." (PMID 37680636, 2023). "TNFSF8/TNFSF15 and TNFSF13 loci are also associated with the risk of IgA nephropathy, while TNFSF4/TNFSF18 locus has previously been associated with the risk of eczema, asthma and narcolepsy, all with concordant effects to IgA levels." (PMID 36369178, 2022). "Single-cell RNA sequencing of murine asthmatic lung and myeloid-cell-specific Tnfsf15-knockout mice (Tnfsf15 Mac-KO) was performed, and the effects of anti-TL1A interventions were evaluated in allergen-induced asthma models." (PMID 41970030, 2026). "Interestingly, FP alone significantly reduced several pro-inflammatory genes related to ASM and asthma, including IL-6, MMP1, PTGS2, and TNFSF15." (PMID 35578269, 2022).
psoriasis (15 papers, 2013 to 2025). An autoimmune condition characterized by red, well-delineated plaques with silvery scales that are usually on the extensor surfaces and scalp. "Genome-wide association studies have revealed the link of TL1A gene (Tnfsf15) variants with various autoimmune and inflammatory diseases, including psoriasis, IBD, Graves’ disease, uveitis, Behcet’s disease, and systemic lupus erythematosus." (PMID 38348035, 2024). "Genetic variants of the TNFSF15 gene are associated with psoriasis, UC, CD, SLE, asthma, and juvenile idiopathic arthritis." (PMID 39297883, 2024). "Case-control and GWA studies have identified Tnfsf15 gene variants, such as rs6478108 alleles, that associate with increased susceptibility to psoriasis and psoriatic arthritis in populations of European descent." (PMID 30972074, 2019). "In summary, we establish genome-wide significant psoriasis associations at the TNFSF15 locus and identify a series of alleles at established psoriasis loci with plausible evidence for causality based on predicted effects on protein structure and function." (PMID 28973304, 2017). "Single variant analysis detected a previously unreported risk locus at TNFSF15 (rs6478108; P = 1.50 × 10−8, OR = 1.10), and association of common protein-altering variants at 11 loci previously implicated in psoriasis susceptibility." (PMID 28973304, 2017). "Genetic studies have revealed the association of TL1A gene (Tnfsf15) polymorphisms with psoriasis." (PMID 38348035, 2024). "Current studies mostly focus on the role of TNFSF15 in inflammatory diseases such as SLE and psoriasis, its potential roles in HCC yet to be further investigated." (PMID 35311155, 2022).
leprosy (13 papers, 2010 to 2025). Leprosy is a chronic infectious disease affecting primarily the skin and peripheral nervous system. "The IL23R gene encodes the protein responsible for forming a receptor for the cytokine interleukin (IL)-23, and is part of the signaling pathway involving the gene product from another locus associated with leprosy, TNFSF15." (PMID 41430577, 2025). "For example, we have previously shown for variants of the TNFSF15/TNFSF8 genes that leprosy patients with the T1R endophenotype are largely the cause of association with the leprosy exophenotype." (PMID 28222097, 2017). "After dissecting the pattern of genetic associations within the TNFSF15 locus in CD, leprosy and PBC, we used functional annotation to identify the most likely potential causal SNP(s)." (PMID 27507062, 2016). "Several GWAS studies have hinted at associations between the 9q32 region, and specifically the TNFSF15 locus, and diverse pathological states including inflammatory diseases of the gut and infectious diseases such as leprosy." (PMID 27507062, 2016). "For example, the TNFSF15 gene had initially been shown to be associated with leprosy per se by a genome wide association study (GWAS) in a Chinese population." (PMID 26844546, 2016). "Consequently, the replication of the TNFSF15/TNFSF8 association in samples of leprosy patients with a low proportion of T1R is expected to display low power." (PMID 28222097, 2017). "In summary, we provide evidence that variance within TNFSF15 has the potential to affect cytokine expression across a range of tissues and thereby contribute to protection from infectious diseases such as leprosy, while increasing the risk of immune-mediated diseases including CD and PBC." (PMID 27507062, 2016). "Interestingly, the A allele of rs6478109 was associated with higher expression of TNFSF15 in blood; given that the same allele was associated with increased risk of CD, and decreased risk of leprosy, it follows that high expression of TNFSF15 will increase CD risk, but decrease leprosy risk." (PMID 27507062, 2016). "In total, 15 SNPs located in five loci—HLA-DR–DQ, RIPK2, TNFSF15, NOD2 and CCDC122-LACC1—were significantly associated with leprosy (p < 1.00 × 10−10)." (PMID 30116885, 2018). "In summary, we have performed a fine-mapping and functional annotation analysis of the TNFSF15 locus in leprosy, CD and PBC." (PMID 27507062, 2016). "Here, we found a borderline decrease (p<0.1) of this mRNA expression in the THP-1 model and our data was unable to clarify the role of TNFSF15 in leprosy." (PMID 23798993, 2013). "Other SNPs identified in the leprosy, tuberculosis and Crohn's-susceptibility studies have identified common genes including IRGM, LRRK2 and TNFSF15 suggesting that a theme of host microbial defence underlies the pathogenesis of these diseases." (PMID 20531959, 2010). "Like TNFSF15, LRRK2 is a gene with an uncertain role in leprosy per se susceptibility." (PMID 26844546, 2016). "That rs4979462 is also associated with risk of leprosy suggests that the transcriptional regulation of TNFSF15 in gastrointestinal or epithelial/connective tissues might play a previously-unappreciated role in the development of leprosy." (PMID 27507062, 2016). "Thus, the leprosy susceptibility loci, including NOD2, RIPK2, TNFSF15, LACC1, LRRK2, IL12B, and HLA‐DR in phagocytes and IL23R, TYK2, and CSK in T cells, may interfere with the synergistic antimicrobial response between phagocytes and T cells." (PMID 38020709, 2023). "Interestingly, when these families were stratified by the T1R status of leprosy patients, variants located in two genes that could not be replicated for leprosy per se—TNFSF15 and LRRK2—were found associated with T1R." (PMID 30116885, 2018). "Moreover, signals of DNase‐seq, H3K4me3 ChIP‐seq, or H3K27ac ChIP‐seq were observed in skin or PBMCs in SNPs among the previously identified known leprosy loci, including loci that EGR2, TNFSF15, RAB32, and NOD2 located in." (PMID 38020709, 2023).
leprosy (continued). "A stepwise association study of leprosy and the non-HLA genes that were significantly associated in the GWAS (RIPK2, TNFSF15, NOD2 and CCDC122-LACC1) was conducted in four independent Brazilian population samples." (PMID 30116885, 2018). "Taken together, these results indicate that variance at rs6478108 and rs4979462 has independent effects on risk of CD, and possibly of leprosy, but not in the Japanese PBC dataset where rs4979462 remains the top SNP within the TNFSF15 locus." (PMID 27507062, 2016). "Of the genes reported by the GWAS, the TNFSF15 and LRRK2 were the only leprosy susceptibility genes not validated for association with leprosy per se in a Vietnamese population." (PMID 26844546, 2016). "To resolve this situation we performed an integrated fine-mapping study of the TNFSF15 locus using published genetic data from PBC patients and controls in a Japanese population, CD patients and controls in a Korean population, and leprosy patients and controls in a Chinese population." (PMID 27507062, 2016). "Finally, we cannot exclude the possibility that NOD2, TNFSF15 and RIPK2 are not true leprosy susceptibility loci." (PMID 20617178, 2010).
ulcerative colitis (13 papers, 2009 to 2024). An inflammatory bowel disease involving the mucosal surface of the large intestine and rectum. "The first genome-wide association study of CD provided evidence that variation in TNFSF15, the TL1A gene, contribute to CD in Japanese and both CD and ulcerative colitis in the British population." (PMID 19262684, 2009).
ankylosing spondylitis (6 papers, 2013 to 2022). An autoimmune chronic inflammatory disorder characterized by inflammation in the vertebral joints of the spine and sacroiliac joints. "In addition to IBD, TNFSF15 gene polymorphism rs4263839 is associated with susceptibility to irritable bowel syndrome and ankylosing spondylitis in Caucasians, and we recently found that TNFSF15 gene polymorphism rs4979462 is associated with susceptibility to PBC in a Japanese population." (PMID 24453414, 2013).
breast carcinoma (6 papers, 2017 to 2023). "In another study, authors indicated that TNFSF15 rs6478106 is related to the risk of breast cancer in Chinese Han population." (PMID 30736740, 2019). "Similar results of TNFSF15 haplotype analysis were discovered in IBD, breast cancer, SLE, CD, and UC, although the composition of the haplotypes was different from that found in our study." (PMID 33287909, 2020). "In addition, breast cancers (BRCA) with high expression of CCL5 and TNFSF15 and ovarian cancers (OV) with high expression of CXCL10 exhibited better prognoses." (PMID 37980406, 2023).